SKP2 (S-phase kinase associated protein 2)
Diseases named in the same sentence as SKP2 in open-access papers (continued):
Sharing a sentence is not in itself a finding about the gene and the disease.
tumor (292 papers, 2005 to 2026). "S-phase kinase-associated protein 2 (Skp2), an E3 ubiquitin ligase, influences the cell cycle by degrading tumor suppressor genes like p21, p27, and p57, as well as causing the ubiquitination and degradation of ACE2 in lung epithelial cells." (PMID 41303587, 2025). "In our tumor samples, we observed the overexpression of S-phase kinase-associated protein 2 (SKP2) and downregulation of cyclin-dependent kinase inhibitor 1C (CDKN1C)." (PMID 40266039, 2025). "The cytosolic SKP2 activates AKT and PTEN loss, implicating SKP2 translocation from the nucleus to the cytosol through Ser72 phosphorylation and induces tumor growth." (PMID 38559562, 2024). "This ubiquitination of AKT associates closely with functions of AKT protein in tumor development, such as cell membrane recruitment, mitochondrial localization, especially increasing the Skp2 level by this AKT-Skp2 positive feedback loop." (PMID 37089937, 2023). "For example, Skp2 mediates the K48-linked ubiquitination of p27 and p21, both of which are tumor suppressors, resulting in the proteasomal degradation of these proteins and cell-cycle promotion." (PMID 37089937, 2023). "Skp2 (S-phase kinase-associated protein 2) is an E3 ligase subunit that is involved in CRC tumor development by increasing HK2-mediated aerobic glycolysis." (PMID 36755301, 2023). "Conversely, APC/CCDH1 has been associated with a tumour suppressive role as majority of its substrates including SKP2 are known oncoproteins." (PMID 36881608, 2023). "Further, the research revealed the close association of SKP2 expression with DNA methyltransferases, mismatch repair genes, microsatellite instability, tumor mutational burden, neoantigen count, and immunity." (PMID 37308972, 2023). "Given that SKP2 expression was associated with at least two clinical characteristics among five neoplasms (BRCA, KIRP, LIHC, LUAD, and READ), covariate analysis was performed for these neoplasms." (PMID 37308972, 2023). "If the accumulation of p27 caused by the down-regulation of SKP2 is inhibited, the degree of cell cycle arrest will be reduced, indicating that the down-regulation of SKP2 causes the accumulation of p27, which causes tumor cells to arrest in the G1/S phase." (PMID 36770809, 2023). "In colorectal carcinoma, CDKs interacting with SKP2 contributed to the loss of tumor differentiation and decreased the OS." (PMID 34869393, 2021). "A positive SKP2 expression was significantly associated with smaller tumor size, lower T category, lower N category, lower stage group, lower recurrence rate, less lymphatic invasion, and less vascular invasion." (PMID 34414959, 2021). "SIRT7 hyperphosphorylation achieves anti-tumor activity by disrupting the SKP2-SCF E3 ligase, thus preventing SKP2-mediated K63-linked AKT polyubiquitination and subsequent activation." (PMID 34433808, 2021). "S-phase kinase-associated protein 2 (Skp2), as an F-box protein, has been characterized to play a critical role in oncogenesis and tumor progression via targeting substrates for ubiquitination and degradation." (PMID 32626765, 2020). "The importance of SKP2 in SCCs pathogenesis is also enlightened by the fact that SCC-associated oncogenic events enhance Skp2 expression and activity in tumor cells." (PMID 32560247, 2020). "Skp2 has been found to be up-regulated in many types of tumors including MM, and up-regulated Skp2 is associated with rapid tumor progression and short survival time of patients." (PMID 31038581, 2019).
tumor (continued). "Overexpression of SKP2 leads to reduction of P27, which is strongly associated with aggressive tumor behavior and poor clinical outcome, while knockdown of SKP2 resulted in the accumulation of P27, causing cell cycle arrest at G1/G0 phase." (PMID 30967999, 2019). "Through activation of protein kinase C iota (PKCiota)-S phase kinase-associated protein 2 (SKP2) signaling pathway, p62 enhanced cell apoptosis resistance and thus promoted tumor growth." (PMID 29738493, 2018). "Deficiency of TRAF6 or Skp2 impairs K63-linked ubiquitination, cell membrane localization and activation of Akt, resulting in tumor suppression in mouse tumor models." (PMID 30413706, 2018). "Mechanistic studies revealed that G0/G1 arrest and tumor senescence upon pulsed T treatment were associated with a marked decrease in cyclin D1, c-Myc and SKp2, CDK4 and p-Rb levels and upregulation of p27 and p-ERK1/2." (PMID 29371946, 2017). "We also found that S-phase kinase-associated protein 2 (Skp2), a protein involved in p27 ubiquitylation and degradation, inversely correlated with p27 both in LNCaP and CW22Rv1 tumor cells." (PMID 29371946, 2017). "It is frequently observed that high Cks1 expression is correlated with high SKP2 and low p27Kip1 and is associated with tumor progression in some cases." (PMID 28061788, 2017). "SKP2 also is a useful prognostic marker for HNSCC management because SKP2 is highly expressed in the invasive edge of human HNSCC tumor tissues and associated with lymph node-metastasis cases." (PMID 28030848, 2017). "A number of solid tumours including lung, breast, ovarian, prostate, colon and squamous cell carcinoma manifest conditions of high SKP2 accompanied by low p27KIP1considered to be associated with highly aggressive tumours." (PMID 27402801, 2016). "Increased expression of SKP2 has been significantly associated with poor tumor differentiation and poor prognosis in CRC18." (PMID 27417709, 2016). "We found significant difference in expression level between normal and tumor tissues for the SKP2 gene associated with survival (p = 0.034)." (PMID 25575813, 2015). "More specifically, our analysis indicates that the difference in the expression level of the SKP2 between normal and tumor tissues is associated with survival." (PMID 25575813, 2015). "S phase kinase-associated protein 2 (Skp2) has been shown to be required for spontaneous tumor development that occurs in the retinoblastoma protein (pRb) deficient mice." (PMID 26497688, 2015). "In univariate logistic regression analyses, high cytoplasmic Skp2 expression was associated with large tumor size (B = 0.222, p = 0.036), high histological grade (B = 0.261, p = 0.008), and positive HER2 expression (B = 0.158, p = 0.009)." (PMID 23300741, 2012). "The majority of p27 in tumor cells is regulated by ubiquitin degradation, and an upregulation of p27 has been associated with downregulation of skp2 via erbB-2 or EGFR inhibition." (PMID 22322523, 2012). "Cytoplasmic Skp2 expression was associated with larger tumor size, more advanced histological grade, and positive HER2 expression." (PMID 23300741, 2012). "In our study, Skp2 expression significantly correlated with cellularity, high risk, tumour size, mitotic count, and Ki67 expression." (PMID 18474118, 2008). "Univariate analysis was performed for patient age, tumour localization in the GI tract, tumour size, cellularity, cell type, mitosis, necrosis, risk grade, p27Kip1, Skp2, Jab1 and Ki67 expression." (PMID 18474118, 2008). "Skp2 expression was detected in 24 tumours (32%), significantly higher in high risk tumours (p = 0.03)." (PMID 18474118, 2008). "Overexpression of Cks1 was strongly associated with increased Skp2 expression and down regulation of p27Kip1 levels, resulting in aggressive tumor behavior and poor prognosis." (PMID 16168119, 2005). "Higher expression of Skp2 is associated with tumor initiation and progression." (PMID 38559562, 2024).
tumor (continued). "Similarly, transgenic mouse models overexpressing Skp2 have shown tumor growth in various tissues, but the cause of how SKP2 triggers neoplastic transformation is elusive." (PMID 38559562, 2024). "Moreover, high Skp2 mRNA or low MLKL mRNA expression in NSCLC tumor tissues was associated with worse overall survival (OS) by an online tool analysis." (PMID 37532777, 2023). "For stage and tumor grade, we hypothesized that higher stage and grade would be associated with lower levels of SKP2 ubiquitination as classified by our signature." (PMID 35169199, 2022). "On the contrary, the F-box protein SKP2 (S-Phase kinase-associated protein 2) could function as a tumor oncoprotein through mediating the ubiquitylation and degradation of multiple cell cycle regulators." (PMID 35197975, 2022). "Moreover, a high Skp2 protein level is significantly associated with a more advanced tumor stage, as well as lymph node involvement." (PMID 35301297, 2022). "Moreover, high Skp2 expression level is associated with tumor recurrence, especially in tumor metastases to lymph nodes." (PMID 34208465, 2021). "In addition, the SKP2 overexpression also enhanced tumor cell invasion, metastasis, and resistance to apoptosis, and was associated with tumor aggressiveness and poor prognosis." (PMID 30967999, 2019). "Moreover, overexpression of SKP2 (S‐phase kinase‐associated protein 2) was significantly related to advanced tumor stage and grade of the patients with BC." (PMID 31199049, 2019). "Interestingly, upon γ-secretase inhibition we found reduced levels of S-phase kinase-associated protein 2 (Skp2), an inhibitor of p27, that was previously shown to regulate senescence in Ptenpc−/− tumours both by mRNA and protein levels." (PMID 27941799, 2016). "Here, we hypothesized that AKT and HBV CP mutations cooperate to disrupt SKP2, which accelerates tumour proliferation and angiogenesis while inhibiting tumour apoptosis." (PMID 27779207, 2016). "Activation of p27 in Pten-null tumours was associated with decreased Skp2 levels." (PMID 27941799, 2016). "The expression levels of CDX2, survivin, B-cell lymphoma 2 (Bcl-2), Bcl-2-associated X protein (Bax), cyclin D1, s-phase kinase-associated protein 2 (Skp2) and c-Myc in the tumor cells were analyzed by western blotting and semi-quantitative reverse transcription polymerase chain reaction." (PMID 25738600, 2015). "Furthermore, our results, together with previous reports, support that Skp2 deficiency restrains cell proliferation and tumor progression by triggering cellular senescence, chromatin remodeling and histone modifications." (PMID 25596733, 2015). "Furthermore, the accumulation of cytoplasmic Skp2 due to Akt-elicited Skp2 phosphorylation at serine 72 was associated with tumor cells expressing elevated Akt or reduced PTEN." (PMID 25115390, 2014). "Furthermore, work in SKP2 knockout mice demonstrated that SKP2 is necessary for tumor formation induced by PTEN, p19ARF, or Rb deficiency." (PMID 23226679, 2012). "Studies have repeatedly shown that Skp2 enhances tumor progression and is independently associated with poor prognosis, suggesting that it may be a novel potential target for intervention." (PMID 18644126, 2008). "However, the correlation of Skp2 expression with several parameters of malignant potential (cellularity, high risk, tumour size, mitotic count, and Ki67 expression) suggests an important auxiliary role of Skp2 in predicting the aggressive potential of GIST." (PMID 18474118, 2008). "Thus, increased expression of Skp2 in these tumors was associated with low p27Kip1 levels, aggressive tumor behavior, and poor overall survival." (PMID 16168119, 2005). "Furthermore, high SKP2 (S-phase kinase associated protein 2) levels were correlated with advanced tumour stage and lymph node invasion and among patients that received chemotherapy and radiation therapy, those with high SKP2 expression levels had poorer overall survival." (PMID 32429269, 2020).
tumor (continued). "To directly test whether Rb loss in a breast epithelial cell could cause synthetic lethality with SKP2 inhibition, we silenced SKP2 using two different siRNAs in non-tumour breast epithelial MCF10A cells expressing either a shRNA silencing RB1 or a non-silencing control shRNA." (PMID 29915391, 2018). "Thus SKP2 gene amplification is likely to be associated with advanced tumor progression." (PMID 27417709, 2016). "In multiple studies, genetic inactivation of SKP2 can prevent tumor initiation and block tumorigenesis." (PMID 41542047, 2026). "Next, we examined the expression status of SKP2 on TMAs of prostate tissues with different pathology including hyperplasia, tumor adjacent tissue, PIN, adenocarcinoma, and normal prostate tissues." (PMID 41542047, 2026). "This emerging evidence clearly has pointed to a central role of SKP2 in regulating IFN-a/γ in the tumor microenvironment through multiple mechanisms." (PMID 41542047, 2026). "The in vivo experiments supported these findings, indicating that RA not only thwarted tumor growth but also substantially lowered the expression of Skp2, EMT markers, and stemness indicators." (PMID 39744562, 2025). "In recent years, studies have found that inhibition of SKP2 can induce DNA replication pressure and genomic instability, thereby activating the inherent immune signaling pathway of tumor cells." (PMID 40534867, 2025). "The ubiquity of S phase kinase-associated protein 2 (Skp2) overexpression in GBM, a protein implicated in both EMT and stemness traits, correlates with increased drug resistance, elevated tumor grades, and adverse outcomes." (PMID 39744562, 2025). "The editing process that ADAR2 mediates increases the expression of CDC14B, which in turn lowers Skp2 levels and promotes tumor suppression." (PMID 40852728, 2025). "Previous studies have demonstrated that elevated expression of SKP2 enhances glycolysis and facilitates tumor progression by promoting the degradation of isocitrate dehydrogenase 1 (IDH1)." (PMID 41241099, 2025). "This mechanistic cascade (CDC14B/Skp2/p21/p27 axis) illustrates a clear pathway by which ADAR2 editing activity constrains tumor cell growth." (PMID 40852728, 2025). "TRIM69, Ube2j1, ZBTB4, and SKP2 show the most pronounced effects on the immune microenvironment of the tumor." (PMID 40697329, 2025). "PDCD11 silencing decreased the levels of the C‐MYC oncoprotein and its target genes, including SKP2, leading to suppressed tumor progression." (PMID 40051297, 2025). "In conclusion, our results demonstrate that RPL35A binds to MYC via its 2 to 22 amino acid residues, thereby facilitating MYC-dependent SKP2 transcription, enhancing glycolysis, and promoting tumor progression." (PMID 41241099, 2025). "These core genes—TRAF4, UBE2L3, FBXO45, UBE2L6, FBXL14, SKP2, CHAF1B, and WDR77—have been implicated in tumor progression in previous studies." (PMID 40990020, 2025). "It is worth noting that the tumor inhibitory effect of SKP2 deletion on immunodeficient mice is weaker than that of immunocompetent mice, indicating that its antitumor effect is highly dependent on the reshaping of the immune microenvironment." (PMID 40534867, 2025). "Specifically, ASBP-AH3 reduces SKP2 and cyclin D1 levels while upregulating p21, thereby disrupting the cell cycle and suppressing tumor growth." (PMID 40004973, 2025). "Enhanced cell cycle progression driven by SKP2 can lead to faster tumor cell growth, making it more challenging for drugs to keep pace with cell division." (PMID 38559562, 2024). "Dioscin inhibits glycolysis by inducing Skp2 ubiquitination and inhibiting HK2 in tumor tissues, which is dependent on the Skp2-Akt-HK2 axis." (PMID 39330497, 2024).
tumor (continued). "Another promising E3 ligase target within the SCF (Skp1–cullin–F‐box) complex is the F‐box protein Skp2, which is overexpressed in various cancers and involved in tumor regulation." (PMID 39329019, 2024). "The in vivo data indicate that SKP2 is a critical contributor to AKT-dependent hepatocarcinogenesis downstream of FASN via its ability to downregulate the p27KIP1 tumor suppressor." (PMID 39064589, 2024). "Surprisingly, following depletion of the SKP2, tumor development is dramatically reduced by inducing programmed cell death and cell senescence." (PMID 38559562, 2024). "In the current study, TKO cells formed fewer tumor spheres and exhibited a lower ALDH activity and self-renewal capacity compared to DKO cells, suggesting that SKP2 plays an essential role in maintaining tumor-initiating properties in OS." (PMID 38355807, 2024). "Together, these results suggest that SKP2 inhibitors exerted a consistent anti-tumor activity in DKO OS." (PMID 38355807, 2024). "SKP2 is a pivotal component of the E3 ubiquitin ligase that controls the turnover of p27KIP1 and other critical tumor suppressor genes by triggering their proteolysis." (PMID 39064589, 2024). "The use of Skp2 inhibitors to elevate IDH1 protein levels has been shown to redirect tumor cell metabolism toward a more functional TCA cycle, effectively curbing malignant proliferation." (PMID 39611141, 2024). "As a tumor suppressor, pRb inhibits SKP2 activities through multiple pathways, involving both transcriptional and post-translational mechanisms." (PMID 38355807, 2024). "PCNA staining was reduced in TKO tumors when compared to DKO tumors, indicating that Skp2 deletion suppresses tumor proliferation." (PMID 38355807, 2024). "Western blots of tumor lysates from four animals in each group showed elevated p27 protein levels with corresponding decreases in Skp2." (PMID 38355807, 2024). "Tumor suppressor miR-340 represses, the Skp2 expression, inhibits tumor cell proliferation, migration, and invasion, and induces apoptosis in hepatocellular carcinoma." (PMID 38559562, 2024). "Overexpression of skp2 also showed a significant correlation with older age, poor patient survival, and high histological grades of the tumor." (PMID 38489280, 2024). "This study demonstrated that SKP2 plays a significant role in tumor progression and drug resistance." (PMID 38559562, 2024). "In contrast, C1 and Pevonedistat exerted minimal inhibitory effects on TKO and mOB cells, suggesting that these drugs are selective for SKP2-expressing tumor cells." (PMID 38355807, 2024). "We found that inhibition of Skp2 expression significantly suppressed tumor growth in the H23 xenograft model." (PMID 37532777, 2023). "Knockdown of Skp2 is more effective in increasing cisplatin cytotoxicity in cisplatin-resistant cells, suggesting Skp2 is likely to be a more promising target in treating cisplatin-resistant tumor cells." (PMID 37532777, 2023). "The current study comprehensively highlights the expression levels and clinical roles (e.g., prognosis) of SKP2 in a series of neoplasms based on thousands of samples from several sources." (PMID 37308972, 2023). "SKP2 plays an essential role in multiple neoplasms, and the corresponding mechanisms require investigation." (PMID 37308972, 2023). "SKP2 is overexpressed in a variety of tumors and is positively correlated with tumor progression and poor prognosis." (PMID 36770809, 2023). "We identified an intronic regulatory region highly enriched for the enhancers’ histone mark H3K27ac within the SKP2 locus of RMS tumor samples and cell lines compared to normal muscle cells." (PMID 38102140, 2023).